IL10 (interleukin 10)
Diseases named in the same sentence as IL10 in open-access papers (continued):
Sharing a sentence is not in itself a finding about the gene and the disease.
lupus (continued). "Specifically, AhR signaling in macrophages has been reported to promote anti-inflammatory M2 phenotype with increased IL-10 production in mouse models of lupus, associated with reduced production of anti-dsDNA autoantibodies." (PMID 30944419, 2019). "IL-10 concentration was associated with depressive symptoms in the RA patients, healthy controls, and the lupus patients." (PMID 30148175, 2018). "The polymorphisms -1082 A>G, -592C>A, and 819C>T in the IL-10 gene seem to modulate the IL-10 levels in different disorders, such as cancer, tuberculosis, systemic lupus erythematosus, and rheumatoid arthritis, but the results are controversial." (PMID 30186038, 2018). "We reported here that deliberate inhibition of selected DLK1-Dio3 miRNAs such as miR-154, miR-379, and miR-300 significantly reduced the production of lupus-associated cytokines IFNγ, IL-1β, IL-6, and/or IL-10." (PMID 27070142, 2016). "Studies of murine models of lupus have identified both pathogenic and suppressive roles for IL-10 in disease." (PMID 26964093, 2016). "A number of observational studies have been conducted to investigate the association of the IL-10 gene polymorphisms with systemic lupus erythematosus (SLE) susceptibility." (PMID 23936042, 2013). "Polymorphisms in IL23R have been associated with Crohn’s disease, rheumatoid arthritis and ankylosing spondylitis, and variants of IL10 have been associated with ulcerative colitis and systemic lupus erythematosus." (PMID 24286189, 2013). "This pharmacological study also argued the role of so-called pathogenic role of IL-10 in the pathogenesis of lupus." (PMID 22389703, 2012). "Some published work reported that, in lupus, pathogenic T cells were comprehensive activated and less sensitive to the suppression of Treg or IL-10." (PMID 22389703, 2012). "The mechanisms underlying TNF-α inhibitor–induced lupus are less well understood but may involve IL-10 upregulation, B-cell hyperactivity, T-helper 2 (Th2)–driven B-cell activation or reduced cytotoxic T-cell apoptosis." (PMID 41283475, 2025). "Importantly, we proved that the deficiency of Hspa13 contributed to impaired IL‐10 production and immune regulatory function of MZ B cells, both in vitro and in lupus mice." (PMID 39737854, 2025). "In lupus, the deficiency in IL-10-producing B cells has been related to worse disease outcomes." (PMID 40761803, 2025). "In addition, a higher risk of systemic lupus erythematosus in Iranian patients was observed at the IL10 rs1800871 CC genotype." (PMID 36882862, 2023). "In addition, the MCODE analysis also associated with systemic lupus erythematosus, HDACs, and IL‐10 and ‐4 signaling." (PMID 37006463, 2023). "In systemic lupus erythematosus, the expression of AhR is increased on the surface of macrophages susceptible to apoptotic cells, which eventually promotes the secretion of immunosuppressive cytokine IL-10; thus, limits the pathogenesis of SLE in-vivo." (PMID 36601108, 2022). "The Post-transplant CD8 T cells suppressed by secreting mainly TGF-β and they expressed high levels of TGF-β latency-associated peptide (LAP), but they produced IL-10 to a much lesser extent; which is desirable because IL-10, by causing expansion of autoimmune B cells, is deleterious in lupus." (PMID 33936042, 2021). "Also, polymorphisms of TGF-β and IL-10 with common variable immunodeficiency, inflammatory bowel disease, chronic idiopathic urticaria and Systemic Lupus Erythematosus (SLE) have been previously investigated 17–24." (PMID 31908741, 2019). "Furthermore, decreased renal levels of Foxp3 and IL-10 are associated with glomerulonephritis in pristane-induced lupus mice." (PMID 31488076, 2019). "In addition, in a follow-up study, a SNP in the Atg5 gene, rs573775, was identified to be related to IL-10 production and higher risk of lupus." (PMID 30108582, 2018).
lupus (continued). "We next investigated whether the hyper-responsiveness of DKO BMDCs to TLR4 stimulation would extend to IFNβ, another key cytokine produced by DCs, which together with IL-10, has been implicated in lupus pathogenesis." (PMID 26544714, 2015). "For example, in MRL/lpr mice, deficiency of IL-10 resulted in exacerbated disease, demonstrated by enhanced Th1 cell development and increased mortality; Over-expression of IL-10 in lupus-prone NZM2410 mice could ameliorate lupus diseases." (PMID 22389703, 2012). "SM934 treatment could correct pathogenic helper T cell commitment and enhance IL-10 production that might be beneficial for future lupus treatment." (PMID 22389703, 2012). "Interestingly, SLC11A1 has been shown to suppress IL-10 production, and the gene that encodes IL-10 has recently been associated with T1D susceptibility, as well as with risk of ulcerative colitis and of systemic lupus erythematosus." (PMID 21524304, 2011). "The synthesis of IL-17 may be linked to increased B-cell production of IL-10 in lupus that also potently promotes humoral immunity." (PMID 20334681, 2010). "Immune control: Low expression of miR-410 in T cells causes elevated levels of the cytokine interleukin-10 (IL-10) in the autoimmune illness systemic lupus erythematosus (SLE)." (PMID 41361288, 2025). "On the contrary, as IL10 is a growth and differentiation factor for B-cells, it is a pathogenic factor in Systemic Lupus Erythematosus (SLE)." (PMID 29799517, 2018). "Recent genome-wide association studies (GWAS) have demonstrated tight association of polymorphisms in the genes encoding IL10 with systemic lupus erythematosis (SLE) and Bechet's disease (BD)." (PMID 22969768, 2012). "The results of these studies are explained by the intrinsically high levels of IL-10 related to lupus susceptibility and severity through the promotion of B-cell proliferation, and immune stimulation by this cytokine seems to trump immunesuppression in lupus patients." (PMID 23554785, 2012). "Estrogens generally enhance humoral autoimmunity and stimulate the T-cell response typical of lupus, leading to increased production of cytokines such as IL-4, IL-5, IL-10, and IL-13." (PMID 40283389, 2025). "High values of IFNγ and IL10 in mouse sera are characteristic of the severe stage of the disease with unstable levels and fluctuations of these important for lupus cytokines." (PMID 40806179, 2025). "High levels of proteinuria and hematuria combined with unstable levels of IL10 and IFNγ promote the development of severe lupus and shorten the survival of treated MRL/lpr mice." (PMID 40806179, 2025). "Interleukin-10 (IL-10) presents a dual role in systemic lupus erythematosus (SLE), illustrating pro-inflammatory and anti-inflammatory effects." (PMID 40244128, 2025). "In lupus patients, IL-10-producing regulatory B cells have been shown to be significantly impaired in number and function, with memory IL-10+ B cells showing the most marked reduction compared with healthy controls." (PMID 40761803, 2025). "TLR7/9-activated IRF5 elevates IL-10 in systemic lupus erythematosus (SLE) models, contrasting with its pro-inflammatory role in TLR2/4-mediated pathways." (PMID 40980176, 2025). "Lupus mice exhibit upregulated expression of both inflammatory (i.e., IL-17, IL-6) and anti-inflammatory (i.e., IL-10) cytokines in brain tissue, a finding readily seen in the periphery of lupus patients." (PMID 38600510, 2024). "In the T cells of lupus patients, the expression of transferrin receptors was correlated with disease severity, and blocking this receptor in vitro enhanced IL-10 production." (PMID 38965216, 2024). "IL-10, typically an anti-inflammatory cytokine, paradoxically enhances B-cell survival and antibody production in lupus patients, worsening the disease despite its usual role in limiting immune responses." (PMID 39329714, 2024).
lupus (continued). "In vivo blocking of IL-10 starting after disease onset increases the production of autoantibodies and lupus pathogenesis." (PMID 38665907, 2024). "Treating lupus-prone mice with these antibodies reduced kidney and liver damage and increased the production of the anti-inflammatory factor IL-10." (PMID 38965216, 2024). "Costimulation by CD3/CD46 proteins leads to IL-2 dependent Tr1-like cells with high IL-10 and low IFN-γ level production, which is associated with disease activity in lupus patients." (PMID 37771588, 2023). "The capacity of B cells from lupus patients to produce IL-10 cytokines upon TLR9 engagement becomes less efficient with increasing disease activity." (PMID 37771588, 2023). "As a result, we identified that 7 of the 12 clusters had significant cluster marker overlaps with Breg subset genes indicating that these clusters represented transcriptionally distinct subpopulations of IL-10+ B cells from pre-disease lupus mice." (PMID 38155972, 2023). "Some studies reported that MDSCs ameliorated systemic lupus erythematosus (SLE) or rheumatoid arthritis (RA) like symptoms in mouse models by inhibiting Th17 cells differentiation or promoting IL-10+ B cells expansion." (PMID 36746935, 2023). "Consistently, the high expression of IL-10 has also been reported in Tph cells in patients with systemic lupus erythematosus (SLE)." (PMID 37762039, 2023). "A specific PKA isoform in common variable immunodeficiency (CVID) and systemic lupus erythematosus (SLE) is associated with increased T lymphocyte activation and diminished IL-10 production." (PMID 36834508, 2023). "Monocytes are the primary source of the T helper 2 (Th2) cytokines IL-6 and IL-10 in the peripheral blood, which are elevated in lupus patients." (PMID 37198993, 2023). "This study provides insights into differences in IL-10 producing B cells generated from lupus-prone mice before disease onset and in the context of active autoimmune inflammation." (PMID 38155972, 2023). "Our initial measurement of serum IL-10 and IL-10 produced by activated IL-10+ B cells indicated that both were significantly decreased in lupus-prone mice with active disease." (PMID 38155972, 2023). "Consistently, we also found that plasma level of IL-10 in lupus patients were higher than those in normal subjects and positively correlated with peripheral RNASE2 expression." (PMID 35265065, 2022). "Levels of IL-10 mRNA and protein secretion in culture supernatants were both down-regulated after silencing of RNASE2 silencing, suggesting that RNASE2 promotes IL-10 production in lupus monocytes." (PMID 35265065, 2022). "The dual and opposing roles IL-10 has in lupus was recently depicted in New Zealand Black x New Zeeland White F1 mice were in vitro experiments revealed pro- and anti-inflammatory IL-10 effects." (PMID 35979356, 2022). "Once again, IL-10 levels were largely decreased in lupus relatives who reported chronic fatigue in both cohorts." (PMID 35720322, 2022). "Serum IL-10 levels have been reported to be increased in lupus patients and correlated with disease activity and anti-dsDNA antibodies." (PMID 35265065, 2022). "IL-2 and IL-10 depletion and a shift to the Th-1 pathway in the innate response are the correlated mechanism for tumor necrosis factor-alpha inhibitor-induced systemic lupus erythematosus." (PMID 35733860, 2022). "In vivo blockade of IL-10 starting after start of the disease at the age of 5 months increase production of autoantibodies and lupus pathogenesis." (PMID 35979356, 2022). "Research done on lupus-prone B6.Sle1.Sle2.Sle3 mice depicted elevated levels of IL-10 from B lineage cells and CD4+ T cells." (PMID 35979356, 2022). "In B6.NZMc1c4 mice, yet another lupus model, genetic deletion of IL-10 lead to increased production of autoantibodies." (PMID 35979356, 2022).
lupus (continued). "Deletion of either miR-183C or miR-182 alone had no changes on the serum levels of IFNγ, IL-6, or other selected lupus-related cytokines, such as TNFα, IL-10, and IL-17." (PMID 35873462, 2022). "In contrast to the consistent increase in IL-10 in human and murine lupus, its impact on disease pathology is discussed controversially." (PMID 33572870, 2021). "In humans, in vivo effects of therapeutic IL-10-neutralization have only been tested on a cohort of six lupus patients, leading to a reduction in disease severity." (PMID 33572870, 2021). "We next aimed to understand effects of IL-10 on the functionality of individual immune cell subsets derived from donors with manifest lupus using in vitro culture." (PMID 33572870, 2021). "We found pleiotropic IL-10 expression that largely increased with progressing lupus, while IL-10 receptor (IL-10R) levels remained relatively stable." (PMID 33572870, 2021). "In sum, these results point towards rather anti-inflammatory effects of IL-10 on effector functions of innate immune cell subsets from donors with manifest lupus." (PMID 33572870, 2021). "Our aim was to understand regulation and immunologic effects of IL-10 on different immune functions in the setting of lupus." (PMID 33572870, 2021). "Persistently high IL-10 levels have been shown throughout pregnancy in women with systemic lupus erythematosus, possibly as an attempt to immunomodulate the existing inflammation." (PMID 34091589, 2021). "In accordance with our studies, among IL-10+ CD4 T cells accumulating in lupus-prone mice and SLE patients, phenotypes distinct from Treg and/or CXCR5hiPD1hi TFH were noted." (PMID 33572870, 2021). "It has been reported that B cells producing IL-10 can inhibit the development of lupus in a mouse model." (PMID 34150746, 2021). "The serum levels of IL-6, IFN-γ, IL-10, and IL-17A were higher in HCMVpp65422-439-immunized mice at 12 weeks post-immunization (24 weeks of age, lupus group) compared with NZB/W F1 mice treated with PBS (control group) or adjuvant only (adjuvant group)." (PMID 34824318, 2021). "The central question of this study was to explore the regulation of IL-10 and IL-10R expression and IL-10 effects on main immune cells and disease pathology in the setting of lupus." (PMID 33572870, 2021). "Further, we found that in vitro inhibition of specific Dlk1-Dio3 miRNAs such as miR-154, miR-379, and miR-300 in MRL-lpr splenocytes suppressed the production of LPS-induced, lupus-related cytokines such as IFNγ, IL-1β, IL-6, and IL-10." (PMID 34062726, 2021). "DNA co-vaccination cocktail of D2 plus IL-10 in pristane-induced lupus BALB/c mice use in a prophylactic way, improves the renal damage by acting as tolerizing therapy corroborated by the decrease in the levels of proteinuria and anti-nRNP/Sm." (PMID 34705865, 2021). "The increasing expression of IL-10 in NZB/W F1 mice with progressing disease indicates a potential impact of IL-10 on lupus pathogenesis and is in concert with other studies." (PMID 33572870, 2021). "Consistent with that, an increase of Tregs and IL-10 is reported in lupus-prone mice and patients with disease progression." (PMID 34335609, 2021). "This cytokine is an essential modulator of disease activity in human SLE, where patients with lupus produce large amounts of IL-10 correlating with disease activity." (PMID 34705865, 2021). "Specifically, stimulatory IL-10 effects on B cells and autoantibody production are suspected to be responsible for the often reported detrimental IL-10 effects on lupus pathology." (PMID 33572870, 2021). "Apart from B cells, we noted an increase in IL-10 expression in all examined immune cells in mice with established lupus." (PMID 33572870, 2021). "In accordance with our study, the application of in vitro-generated polyclonal IL-10-producing CD4 T cells to severely-ill NZB/W F1 mice improved lupus pathology." (PMID 33572870, 2021).
lupus (continued). "IL2/IL4 and IL2/IL10 ratios have been repeatedly used as markers of inflammation and tissue injury in Systemic Lupus Erythematosus (SLE), or as an indication of cytokine imbalance in vitiligo, also in athletes." (PMID 34271953, 2021). "IL-10R expression critically influences the responsiveness of cells towards IL-10; its relevance in human and murine lupus remains, however, controversial." (PMID 33572870, 2021). "In lupus-prone MRL/lpr animals, IL-10 exerted protective effects by suppressing pathogenic Th1 responses and IFN-γ production." (PMID 33572870, 2021). "Further, we found that during the pre-disease period, administration of activated IL-10 producing Breg cells to mice treated with vancomycin suppressed lupus initiation, and that bacterial DNA from the gut microbiota was an inducer of Breg function." (PMID 33240280, 2020). "In contrast, hypomethylation of IL10 has been reported to promote the incidence of diseases, including Escherichia coli-induced mastitis and systemic lupus erythematosus." (PMID 33193625, 2020). "hsa-miR-410-3p appears to directly target STAT3, leading to a reduction of IL-10 in T cells of patients with systemic lupus erythematosus, and was also shown to be elevated in the plasma of these patients." (PMID 32849505, 2020). "Serum proinflammatory cytokines, including IL-17a, IFN-γ, IL-6, TNF, and IL-2, were significantly increased, while the anti-inflammatory cytokine IL-10 was significantly decreased in sodium chloride-pretreated BMDC-ALD-DNA-induced lupus mice." (PMID 32296043, 2020). "We find that the absence of CD137L worsens glomerulonephritis, dermatitis and survival, and we identify as potential underlying mechanisms a stronger Th17 polarization and/or a reduction in myeloid cell-derived IL-10 in lupus-prone B6.lpr−/− mice." (PMID 31297111, 2019). "This is in line with the previously reported finding that Btk is required for TLR-induced IL-10 production by B cells and that B cells from lupus-prone mice upregulate IL-10 production in response to TLR stimulation, but not to BCR or CD40 engagement." (PMID 30761150, 2019). "Serum IL-10 levels in systemic lupus erythematosus patients with osteonecrosis were higher than that in those without osteonecrosis." (PMID 31795299, 2019). "AhR agonists have also been shown to directly induce IL-10 responses in myeloid cells to counter autoimmune disorders such as lupus." (PMID 30944419, 2019). "In our previous works, we described associations between SNPs in the STAT4, IL10, TRAF3IP2, and HCP5 (HLA complex P5) genes and systemic lupus erythematosus (SLE) susceptibility." (PMID 30882006, 2019). "hCDR1 has suppressive effects on T cells by reducing apoptosis of T cells with less secretion of interferon-γ and upregulation of IL-10 in lupus-prone mice." (PMID 31379858, 2019). "Adoptive transfer of IL-10-secreting Bregs significantly inhibited lupus progression in lupus-prone MRL/Lpr mice." (PMID 31795353, 2019). "Induction of IL-10-secreting Treg cells by anti-CD3 antibody treatment in a lupus-prone model in mice can inhibit the activation of effector T cells (Th1, Th2 and Th17), whereby improving the renal condition in mice." (PMID 31475012, 2019). "In humans, a B cell population that produces IL-10 and inhibits Th1 cell responses is present in the CD24hiCD38hi B cell compartment, and this subset is functionally impaired in patients with systemic lupus erythematosus (SLE)." (PMID 29967611, 2018). "IL-10 seems to be involved in inhibiting some of the clinical/pathologic manifestations of pristane-induced lupus such as diffuse alveolar hemorrhage (DAH)." (PMID 30257456, 2018). "hCG elicited significantly higher levels of IL-10 from cells derived from lupus-prone mice than from healthy mice." (PMID 30574119, 2018). "Several phenotypic B-cell subsets are capable of producing IL-10 upon stimulation and of suppressing inflammatory processes in human but lack the suppressive capacity in systemic lupus erythematosus patients." (PMID 28491871, 2017).